OR2T2 (olfactory receptor family 2 subfamily T member 2)
Description:
Odorant receptor.
Synonyms: OR2T2P; OR1-43
Tractability: Antibody: UniProt places it where antibodies can reach, with medium confidence; UniProt predicts a signal peptide or a membrane-spanning region; its Gene Ontology location is reachable by antibodies, with medium confidence.
Gene: Protein-coding gene on chromosome 1 (248,445,512 to 248,455,725, forward strand). Ensembl gene ENSG00000196240.
Subcellular location: Cell membrane
Pathways (Reactome):
Sensory Perception: Expression and translocation of olfactory receptors
Gene Ontology:
Molecular function: olfactory receptor activity; G protein-coupled receptor activity
Biological process: detection of chemical stimulus involved in sensory perception of smell; G protein-coupled receptor signaling pathway
Cellular component: plasma membrane; membrane
Genetic constraint (gnomAD): Missense variants: 138 observed, 280.49 expected, observed/expected ratio (o/e) 0.49, 90% interval 0.43 to 0.57. Synonymous variants: 50 observed, 96.53 expected, observed/expected ratio (o/e) 0.52, 90% interval 0.41 to 0.66.
Homologues: Orthologues: dog OR2T2 (88% identical), rat Or2t35 (85% identical), mouse Or2t35 (82% identical). Paralogues in human: OR2T35 (99% identical), OR2T11 (68% identical), OR2T27 (66% identical), OR2T1 (65% identical), OR2T29 (63% identical), OR2T5 (63% identical), OR2T4 (60% identical), OR2T10 (60% identical), OR2T6 (60% identical), OR2T3 (57% identical), OR2T34 (56% identical), OR2T33 (53% identical), and 80 more.